FGF21 (fibroblast growth factor 21)
Diseases named in the same sentence as FGF21 in open-access papers (continued):
Sharing a sentence is not in itself a finding about the gene and the disease.
Obesity (continued). "The recently discovered proteins Irisin and FGF-21 are known to be associated with obesity in adulthood; however, little is known about their role in childhood and adolescence." (PMID 33924457, 2021). "Mouse model studies and even some human studies indicated that pharmacological treatment with FGF21 can attenuate comorbidities associated with obesity." (PMID 34019585, 2021). "Conditions associated with overfeeding, including obesity, are also associated with increased systemic FGF21 levels." (PMID 35046901, 2021). "For both genes, the FTO and FGF21, the prevalence of obesity was highest for the homozygous risk alleles, except for the FGF21 rs838145, where the highest obesity prevalence was observed among the heterozygous A/G." (PMID 34095191, 2021). "In humans and animal models, levels of circulating FGF21 associate with increased cardiometabolic risk factors including obesity and dyslipidemia." (PMID 34684643, 2021). "A study in Chinese youths demonstrated that obesity is associated with higher FGF21 on the one hand and higher and lower adiponectin levels on the other hand, which is also in line with our findings." (PMID 33805553, 2021). "The only correlation was found in relation to the weight, and waist circumference, showing an important association of FGF21 protein with the degree of obesity of the individuals." (PMID 34019585, 2021). "In conclusion, our results showed that individuals with overweight/obesity submitted to weight loss therapy demonstrated different responses in relation to FGF21 levels." (PMID 34762789, 2021). "It appears that obesity-related circulating exosomes can impair insulin signaling pathways and associated components, increase intracellular TG content, and decrease FGF21 secretion in the hepatocytes." (PMID 32322309, 2020). "Recent studies show brain-derived neurotrophic factor (BDNF) and fibroblast growth factor 21 (FGF21) are neurotrophic factors associated with obesity and diabetes mellitus (DM)." (PMID 32210348, 2020). "Obesity is generally regarded as an FGF21-resistant state, and weight loss has been shown to be associated with decreasing FGF21 levels." (PMID 33071964, 2020). "The genetic variability of FGF-21 was found to be potentially associated with macronutrient consumption, and risk of obesity and type 2 diabetes in humans." (PMID 32069846, 2020). "Despite the role of FGF21 in metabolism regulation, reports on its usefulness as a biomarker for obesity and abnormalities associated with MS are conflicting." (PMID 32546231, 2020). "Given that FGF21 has been shown to improve insulin sensitivity and promote negative energy balance, some have suggested that obesity and associated metabolic syndrome represent an “FGF21-resistant” state." (PMID 32158768, 2020). "Increased levels of FGF21 are associated with obesity, fatty liver, atherogenic lipid profiles, and reduced bone mineral density." (PMID 33210059, 2020). "Exaggerated fasting and postprandial secretion of GIP in obesity are associated with elevated liver damage markers as well as FGF-21 plasma levels." (PMID 32069846, 2020). "Further studies seem then necessary to assess the effects of weight loss (WL) interventions on FGF21 as a thermogenesis marker in adolescents with obesity." (PMID 32267352, 2020). "The evidences questioning the anti-obesity effects of FGF21 in adolescent with obesity remains scarce, while an association between increased circulating FGF21 and metabolic disorders has been reported in adults." (PMID 32267352, 2020). "A clinical trial in patients with obesity and DM showed that chronic administration of a long-acting form of FGF21 caused a marked elevation of circulating adiponectin levels and an obvious reduction in blood levels of total and LDL-cholesterol." (PMID 32957703, 2020). "The study correlates the demethylation of Fgf21 with a decreased risk of diet-induced obesity in older rodents thus highlighting a link between breastfeeding and suppression of obesity." (PMID 33375554, 2020).
Obesity (continued). "Administration of the FGF21 analogue to people suffering from obesity and type 2 diabetes caused beneficial effects on some disorders associated with diabetes; however, further studies with the analogue are needed." (PMID 30927227, 2019). "In this study, we demonstrate that deficiency of FGF21 aggravates obesity-induced atrophic responses and inflammation in skeletal muscle of mice fed an HFD." (PMID 31312114, 2019). "A previous study suggested that obesity-related adipocyte inflammatory condition can suppress β-Klotho expression by tumor necrosis factor-alpha and impair FGF21 function in adipose tissue causing glucose intolerance." (PMID 31582974, 2019). "In this study, we investigated the effect of FGF21 deficiency on obesity-induced skeletal muscle inflammation and atrophy in mice." (PMID 31312114, 2019). "In humans, a successful therapeutic approach that focuses on designing specific inhibitors of FAP to overcome the FGF21-resistant state associated with obesity and type 2 diabetes would succeed." (PMID 31546675, 2019). "In conclusion, we demonstrate that FGF21 deficiency aggravates the obesity-induced skeletal muscle inflammation and atrophy in the HFD-fed obese mice, accompanied by NF-κB activation and suppression of AMPK phosphorylation." (PMID 31312114, 2019). "FGF21 is induced by metabolic stress caused by conditions such as obesity, non-alcoholic fatty liver disease, and diabetes mellitus, as well as by damage to various organs, which involves mitochondrial and ER stress." (PMID 31408968, 2019). "Enhanced liver production of FGF21 has been linked to obesity, diabetes mellitus, and metabolic syndrome." (PMID 30959789, 2019). "Exogenous FGF21 administration counteracts obesity in several different animal models, and clinical trials have already been conducted in obese human patients utilizing an FGF21 variant, LY2405319." (PMID 30813227, 2019). "In animal models of obesity, as well as in obese patients, FGF21 has been shown to induce body weight loss and to increase insulin sensitivity and lipid homeostasis." (PMID 31374856, 2019). "The present study provides new insight into the protective mechanism of FGF21 against glucolipotoxicity-induced islet dysfunction in obesity-associated T2DM." (PMID 31121855, 2019). "FGF21 is generally believed to decrease blood pressure through its dramatic improvements in lipid profiles as accumulating evidence suggests that obesity and dyslipidemia are key risk factors in the development of hypertension." (PMID 30106981, 2018). "Several studies have shown that FGF21 overexpression in rodents is associated with weight loss and lower obesity, as well as insulin sensitivity in its target tissues." (PMID 30242179, 2018). "Consistent with findings by Lin in mice, administration of an FGF21 analog in type 2 diabetic patients with obesity reduced several cardiovascular risk factors, including insulin resistance, dyslipidemia, and hypoadiponectinemia." (PMID 29949887, 2018). "Nonetheless, the present study found that AAV8‐hAAT‐FGF21 was protected from obesity‐associated liver neoplasms, which in turn argues in favor of a protective role of FGF21 against malignancies in the liver." (PMID 30021799, 2018). "Increasing evidence has proposed that obesity, insulin resistance, and other metabolic diseases are thought to cause a state of FGF21 resistance in both rodents and humans." (PMID 30185439, 2018). "Human studies have reported a positive association of FGF21 serum levels with obesity and ectopic fat depots, which is in agreement with our observations, as well as great variability in FGF21 serum levels." (PMID 30242179, 2018). "The association between adiposity and circulating FGF-21 levels is therefore much stronger in conditions of high adiposity (overweight and obesity)." (PMID 30298107, 2018).
Obesity (continued). "This was parallel to the normalization in the expression of the macrophage markers F480 and CD68 and of the pro‐inflammatory cytokines TNF‐α and IL‐1β, indicating that FGF21 expression counteracted the inflammation of WAT associated with obesity." (PMID 29987000, 2018). "Eli Lilly reported the effects of LY2405319 (LY), a variant of FGF21, in a randomized, placebo-controlled, double-blind, proof-of-concept trial in patients with obesity and type 2 diabetes." (PMID 29949887, 2018). "Among youths at risk for metabolic syndrome, FGF21 levels were positively correlated with obesity traits, blood pressure, and lipid profiles, indicating its essential role in the metabolic system." (PMID 28821258, 2017). "This notion is in line with the finding that Fgf21 serum levels are often elevated in obesity-associated IR, possibly reflecting resistance to Fgf21." (PMID 29091029, 2017). "Given that human ageing is associated with increased risk of obesity and metabolic syndrome, our study highlights the need for further research into FGF21 mediated improvements in metabolically inflexible adipose tissue." (PMID 28652585, 2017). "FGF21 is strongly associated with metabolic disorders like obesity and hyperinsulinemia, which is the main mechanism of development of AN." (PMID 27190511, 2016). "PF-05231023, a long-acting FGF21 analogue, is a promising potential pharmacotherapy for the treatment of obesity and associated comorbidities." (PMID 27405817, 2016). "Obesity is associated with decreased activity of the insulin sensitising effects of fibroblast growth factor-21 (FGF21) due to down regulation of the FGF21 receptor cofactor β-Klotho." (PMID 27338619, 2016). "We also observed that pancreatic FGF21 is nutritionally regulated; a marked reduction in FGF21 expression was noted with fasting while obesity is associated with 3–4 fold higher expression." (PMID 26872145, 2016). "We have demonstrated that metformin suppresses high-fat diet-induced obesity and the associated inflammatory response by inducing FGF21 production in obese mice and HepG2 cells." (PMID 27057099, 2016). "The major risk factors for NAFLD are obesity, dyslipidemia, and insulin insensitivity, which have been shown to be improved by FGF21." (PMID 26441837, 2015). "Paradoxically, however, studies in both mice and humans have shown that obesity is associated with elevated circulating levels of FGF21, suggesting impaired FGF21 signaling." (PMID 26379627, 2015). "FGF21 enhances insulin sensitivity, decreases triglyceride concentrations, and ameliorates obesity-associated hyperglycemia and hyperlipidemia." (PMID 26379757, 2015). "Although both control and the advanced group of rats were fasted for 8–10h before sacrifice, the advanced group showed a decrease in liver Fgf21 and Pparα suggesting a predisposition to obesity." (PMID 25837425, 2015). "SNPs in the 3′ untranslated region of FGF21 are also associated with metabolic syndrome, obesity, and diabetes." (PMID 26483756, 2015). "Obesity and overfeeding increase FGF-21; it has been proposed that obesity causes FGF-21 resistance." (PMID 24465939, 2014). "In humans, increased FGF21 levels are associated with obesity in both children and adults, indicating a connection between FGF21 and body fat mass." (PMID 24488758, 2014). "SNPs in the Fgf21 3′ non-coding region were also associated with metabolic syndrome, obesity, and diabetes." (PMID 25071723, 2014). "As for the recently discovered adipokines, evidence mainly based on cross-sectional studies suggests that A-FABP, chemerin and FGF-21 are significantly associated with early obesity and metabolic abnormalities." (PMID 25356508, 2014).
Obesity (continued). "This indicates that the adipocyte is the specific target of endocrine FGF21, which underlies its therapeutic activities against obesity and diabetes that are also risk factors for some cancers." (PMID 24279986, 2013). "Recent results suggest that FGF21 is highly expressed in hepatocytes under metabolic stress caused by starvation, hepatosteatosis, obesity and diabetes." (PMID 23590285, 2013). "Treatment with pharmacological levels of FGF21 alleviates obesity and associated metabolic diseases including diabetes." (PMID 24385972, 2013). "More recent studies reported that FGF21 levels were increased in association with obesity and NAFLD31." (PMID 24189525, 2013). "We also recently showed that increased FGF21 from skeletal muscle with autophagy deficiency contributes to an improvement of obesity and insulin resistance in muscle-specific Atg7-deficient mice fed HFD compared to control mice fed HFD." (PMID 23667629, 2013). "In the only previous study of FGF-21 levels in HIV infection, the authors found associations of FGF-21 levels with obesity, glycaemia, dyslipidaemia and liver dysfunction, in line with literature from HIV-uninfected patients." (PMID 24252301, 2013). "Our data are also supported collectively by other spontaneous reports indicating that FGF21 is preferentially induced in the liver upon fasting and starvation, steatosis, obesity, type 2 diabetes and genetic deficiency of specific genes in hepatocytes." (PMID 23590285, 2013). "FGF21 levels were positively associated with obesity and the metabolic syndrome and increased in T2DM." (PMID 23755203, 2013). "Based on these findings, we propose that the mechanism of increased FGF21 levels in kidney disease is similar to those observed in obesity-associated resistance to insulin." (PMID 21525989, 2011). "On the other hand, most human studies have linked obesity or IGT with increased FGF21 levels in humans, because most humans in developed countries have more problems with over-nutrition than with starvation." (PMID 21829679, 2011). "Recent human studies indicate that increased circulating levels of FGF-21 are found in obese individuals and subjects with metabolic syndrome or type 2 diabetes and are closely associated with obesity and renal dysfunction in chronic hemodialysis." (PMID 21206918, 2010). "Nevertheless, these data suggest that elevated FGF21 levels in people with obesity may be associated with sarcopenic obesity." (PMID 40171198, 2025). "Taken together, these data suggest that elevated concentrations of FGF21/sTGFBR2 decrease diet-induced adiposity, improve metabolic dysfunction associated with obesity, and increase certain cortical bone variables, particularly when mice are at warmer environmental temperatures." (PMID 40663389, 2025). "Our findings demonstrate significant alterations in circulating levels of FGF19, FGF21, leptin, irisin, and adiponectin, providing evidence that severe obesity is associated with dysregulated organokine networks that contribute to liver disease development and progression." (PMID 40943431, 2025). "The individual loss of endogenous Gdf15 or Fgf21 has been studied in the context of obesity." (PMID 40787810, 2025). "Moreover, plasma levels of FGF21 increase after gastric sleeve surgery, whereas a decrease is detected in individuals with obesity/overweight and MASLD after weight loss." (PMID 40443802, 2025). "The improved pharmacokinetic and pharmacodynamic properties of FGF21-164 underscore its therapeutic potential for addressing metabolic disorders, particularly the obesity-associated dysregulation of glucose and lipid metabolism, and nonalcoholic steatohepatitis." (PMID 40141314, 2025). "FGF21 mitigates inflammation by promoting the M1-to-M2 macrophage transition, thereby protecting tissues from age-related damage, such as liver fibrosis and chronic kidney disease associated with obesity." (PMID 40958908, 2025).
Obesity (continued). "However, FGF21 signaling is frequently impaired in metabolic disorders, including obesity, diabetes, and metabolic dysfunction-associated steatotic liver disease (MASLD)." (PMID 41516073, 2025). "FGF21 can also up-regulate the secretion of adiponectin, an adipokine that plays a vital role in sensitizing the body to insulin, and hypoadiponectinemia caused by various factors can lead to obesity, type 2 diabetes, and metabolic syndrome." (PMID 38292187, 2024). "Weight loss and browning effects of FGF21 persist in obesity as DIO male mice treated daily with FGF21 (1 mg/kg) for 2 weeks experience a 20% reduction in body weight without affecting food intake, and upregulated gene expression of Pgc-1α, and Ucp1 in WAT and BAT compared to controls." (PMID 39087083, 2024). "FGF21 is a newly discovered adipokine released from many organs, including brown adipose tissue, which is thought to prevent metabolic complications associated with obesity by increasing glucose utilization and fat oxidation in the liver." (PMID 39008201, 2024). "FGF21 exerts further anti-inflammatory effects by stimulation of adiponectin, which can enhance lipid and glucose metabolism and therefore mitigate the risk of obesity, diabetes and ASCVD." (PMID 39728000, 2024). "Finally, the utility of our lead DB-lipidoid was demonstrated through hepatic delivery of Cas9 mRNA/sgRNA for gene editing of transthyretin (TTR) and human fibroblast growth factor 21 (FGF21)-encoded mRNA for the treatment of obesity and fatty liver." (PMID 38409275, 2024). "In addition, β-conglycinin feeding for up to 9 weeks kept FGF21 levels in the liver and circulating FGF21 at a certain level, thereby reducing weight gain associated with a high-fat diet and thus ameliorating obesity." (PMID 37111030, 2023). "Apart from weight loss, FGF21 can improve obesity-induced metabolic disorders." (PMID 36594101, 2023). "FGF21 can be a biomarker that reflects the degree of obesity and the effectiveness of weight loss." (PMID 36594101, 2023). "It has been speculated that FGF-21 production could represent a response of the organism to cope with dysmetabolism caused by obesity and MetS." (PMID 37409233, 2023). "Interestingly, high FGF21 concentrations have been associated with obesity and NAFLD, not only in adults, but also in adolescents." (PMID 37685811, 2023). "In this study, we assessed intact and total FGF-21 levels in two cohorts of subjects with putative risk for MetS and obesity-related diseases with the goal of identifying the relationships between FGF-21 serum level and visceral obesity and its related complications." (PMID 37409233, 2023). "Additionally, PPAR-α and FGF-21 promote fat oxidation and thermogenesis in adipose tissue, potentially counteracting metabolic abnormalities linked to obesity." (PMID 38035345, 2023). "The overall objective was to explore if FGF21 could be used safely and efficaciously to treat common obesity-associated metabolic dyscrasias, utilizing a research colony of obese and overweight cats with similar insulin resistance and metabolic alterations." (PMID 36756310, 2023). "In addition, FGF21 is likely a regulator that reverses the decrease in muscle mass caused by obesity or inflammation and improves muscle mass under some special physiological conditions." (PMID 38069273, 2023). "FGF21 levels correlate with various cardiometabolic conditions, and higher FGF21 expression is associated with cardiovascular risk factors such as chronic inflammation, obesity, hypertriglyceridemia, and elevated liver enzymes." (PMID 38139126, 2023). "FGF21 has been associated with obesity, T2DM, and hepatic steatosis, even in pediatric populations." (PMID 37685811, 2023). "Future studies should also investigate the effects of FGF21-linked neural signaling on food cravings and eating behavior as well as how obesity might impact these effects." (PMID 35491674, 2022).